HIF1A (hypoxia inducible factor 1 subunit alpha)
Diseases named in the same sentence as HIF1A in open-access papers (continued):
Sharing a sentence is not in itself a finding about the gene and the disease.
epilepsy (continued). "Through proteomics analysis, we identified that HIF-1α was overexpressed in mice with VPA-resistant epilepsy, and regulated the expression of interleukin-1β and tumor necrosis factor-α." (PMID 34497517, 2021). "HDAC5 silencing reduced apoptosis in epilepsy model cells, which was reversed by HIF1α or PFKFB3 overexpression." (PMID 34021541, 2021). "Bioinformatics analysis of public databases demonstrated that miR-221-3p was reduced in VPA-resistant epilepsy, and negatively regulated HIF-1α expression." (PMID 34497517, 2021). "Taken together, these results show that miR-485 inhibited epilepsy through the HDAC5/HIF1α/PFKFB3 axis in vivo." (PMID 34021541, 2021). "We demonstrated that expression of miR-221-3p, as a potential biomarker, is downregulated in VPA-resistant epilepsy, which leads to increase in expression of its target gene: HIF-1α." (PMID 34497517, 2021). "First, we demonstrated that miR-221-3p mimics markedly increased miR-221-3p expression and 2ME2 evidently reduced the expression of HIF-1α in the hippocampus of mice with VPA-resistant epilepsy." (PMID 34497517, 2021). "Overall, miR-485 inhibited apoptosis, oxidative stress, and inflammation in epilepsy model cells through the HDAC5/HIF1α/PFKFB3 axis." (PMID 34021541, 2021). "We identified that miR-221-3p was down-regulated markedly in VPA-resistant epilepsy, and negatively regulated the expression of the target gene: HIF-1α." (PMID 34497517, 2021). "In nonneuronal cells, mTOR is known to regulate activity, cellular localization, and the level of several transcription factors, e.g., hypoxia-inducible factor 1α (HIF-1α), increased expression of which was reported in animal models of epilepsy." (PMID 26993296, 2017). "Accordingly, targeting HIF-1α represents an attractive strategy to enhance the efficacy of current therapies of refractory epilepsy." (PMID 27554040, 2016). "Activation of the HIF-1α/H -1 pathway is evident as hippocampal neurons in epileptic animal models and epilepsy patients’ brain tissues show marked HIF-1α and HO-1 upregulation, positively correlating with ferroptosis markers like lipid peroxides, ACSL4 increase, and GPX4 inactivation." (PMID 40421132, 2025). "According to the univariate analysis, 13 variables were significantly associated with survival: age, performance status, extent of surgery, tumor depth, tumor size, epilepsy, postoperative chemoradiotherapy, IDH mutations, CD44, HIF-1α, HIF-1β, vimentin, and PDFGR." (PMID 38927417, 2024). "HIF-1α/meme oxygenase 1 may promote the development of epilepsy by inducing ferroptosis of hippocampal neurons and reducing the activity of antioxidant enzymes in hippocampal tissue." (PMID 39876842, 2024). "This study aims to investigate whether the HIF-1α/HO-1 pathway can promote epilepsy by mediating hippocampal ferroptosis." (PMID 37876811, 2023). "In conclusion, our research findings indicated that the HIF-1α/HO-1 pathway might promote the occurrence and development of epilepsy by mediating hippocampal ferroptosis." (PMID 37876811, 2023). "Additionally, analysis of epilepsy disease target genes based on the DisGeNET human disease database further supports HIF-1α as an important disease target gene in human epilepsy." (PMID 37876811, 2023). "Inhibiting the activation of the HIF-1α/HO-1 pathway and regulating iron metabolism may offer potential approaches for epilepsy treatment." (PMID 37876811, 2023). "In this study, we assess the significance of HIF-1α in VPA-resistant epilepsy." (PMID 34497517, 2021). "We investigated the effect of HIF-1α in VPA-resistant epilepsy." (PMID 34497517, 2021). "Therefore, we provide strong evidence that HIF1α is a mediator in the pathway that promotes neuronal injury during epilepsy." (PMID 34021541, 2021). "Our data suggest the effect of miR-221-3p/HIF-1α on VPA-resistant epilepsy." (PMID 34497517, 2021). "Therefore, we investigated the miRNAs that regulate HIF-1α expression in patients with VPA-resistant epilepsy." (PMID 34497517, 2021).
epilepsy (continued). "Subsequently, we demonstrated that miR-221-3p mimics effectively reduce the expression of HIF-1α in the hippocampus of mice with VPA-resistant epilepsy, thereby reducing the number of microglia, inhibiting the release of proinflammatory mediators, and alleviating the number of seizures markedly." (PMID 34497517, 2021). "To test this hypothesis, we surveyed the effect of miR-221-3p mimics and 2ME2 (HIF-1α inhibitor) in VPA-resistant epilepsy." (PMID 34497517, 2021). "Studies on epilepsy-induced rat models and post-mortem human histopathologic brain samples supported a significant correlation between HIF-1a elevation and epilepsy occurrence Numerous analyses have supported the positive correlation between HIF-1 and the elevation of COX-2 production." (PMID 31312171, 2019). "We noticed a close resemblance of the staining pattern of VEGF/HIF-1α/DAPK expression in the epilepsy specimens and other cerebrovascular disorders, such as AVM and BT, suggesting that DAPK expression is correlated to BBB pathophysiology in such brain disorders." (PMID 30414085, 2019). "However, to the best of our knowledge, this is the first work that shows decreased miR-153 level is related to drug-resistant epilepsy through mediating overexpression of HIF-1α." (PMID 27554040, 2016). "Collectively, it suggests that HIF-1α may be a core factor involving drug-resistance of epilepsy and may be a potential therapeutic intervention strategy." (PMID 27554040, 2016). "In epilepsy, hypoxia-inducing factor 1α (HIF1α) has been induced in reactive astrocytes." (PMID 26217188, 2015). "Modulation of HIF-1α may offer a new therapeutic target in epilepsy." (PMID 39408863, 2024). "However, whether the HIF-1α/HO-1 signaling pathway can mediate hippocampal ferroptosis and contribute to the occurrence and development of epilepsy remains unclear." (PMID 37876811, 2023). "Therefore, we propose a scientific hypothesis that the HIF-1α/HO-1 pathway promotes the occurrence and development of epilepsy by mediating hippocampal neuronal ferroptosis." (PMID 37876811, 2023). "Furthermore, the activation of the HIF-1α/HO-1 pathway may reduce the activity of antioxidant enzymes in hippocampal tissue, further exacerbating oxidative damage in hippocampal neurons and the progression of epilepsy." (PMID 37876811, 2023). "Western blotting in mice hippocampal tissue was carried out, and results indicated that expression of HIF-1α, IL-1β, and TNF-α in the hippocampus of mice with VPA-resistant epilepsy was upregulated compared with that in mice with VPA-sensitive epilepsy." (PMID 34497517, 2021). "We systematically assess the significance of HIF-1α on children and mice with VPA-resistant epilepsy, and investigated the micro (mi) RNAs that regulate HIF-1α expression." (PMID 34497517, 2021). "In conclusion, miR-485 alleviates epilepsy through inhibition of HDAC5, leading to downregulation of HIF1α and PFKFB3." (PMID 34021541, 2021). "The forced HDAC5 overexpression increased HDAC5, HIF1α, and PFKFB3 expression in the presence of miR-485 mimic in epilepsy model cells, but increased HIF1α and PFKFB3 expressions only in the presence of miR-485 mimic." (PMID 34021541, 2021). "Since this study focused on the role of HIF-1α in VPA-resistant epilepsy, we prioritized IL-1β and TNF-α that directly interact with HIF-1α." (PMID 34497517, 2021). "We sought to identify the miRNA that regulates HIF-1α expression in a mouse model and in patients with VPA-resistant epilepsy." (PMID 34497517, 2021). "Collectively, we find that miR-485 alleviates epilepsy by inhibiting HDAC5, HIF1α, and PFKFB3 expression, thus presenting therapeutic targets for the treatment of epilepsy." (PMID 34021541, 2021). "Hypoxia-inducible factor-1alpha (HIF1α) is a pro-inflammatory downstream mediator of HDAC5, which can promote epilepsy." (PMID 34021541, 2021). "However, the contribution of HIF-1α in VPA-resistant epilepsy remain unknown." (PMID 34497517, 2021).
epilepsy (continued). "Given the involvement of PFKFB3 is involved in neuronal excitotoxicity, which is an important mechanism for epilepsy, we set about to investigate the interactions among miR-485, with HDAC5, HIF1α, and PFKFB3 in cellular and animal models of epilepsy." (PMID 34021541, 2021). "Proteomics analysis revealed that overexpressed HIF-1α interacted with IL-1β and TNF-α in mice with VPA-resistant epilepsy, which was also confirmed by western blotting." (PMID 34497517, 2021). "Seizure progression and neuronal stress during epilepsy triggers the DAPK pathways, which regulate HIF-1α and angiogenesis genes and proteins (e.g., VEGF) and other factors responsible for BBB function in health and disease." (PMID 30414085, 2019). "We assessed DAPK localization with hypoxic inducible factor (HIF-1α) and vascular endothelial growth factor (VEGF) in epilepsy, BT, and AVM." (PMID 30414085, 2019). "miR-485 mimic reduced HDAC5, HIF1α, and PFKFB3 expressions in epilepsy model cells." (PMID 34021541, 2021). "Hypoxia-inducible factor (HIF)-1α is an essential effector molecule of hypoxia and inflammation, and may exert therefore a significant effect on the development of VPA-resistant epilepsy." (PMID 34497517, 2021). "Intervention using miR-221-3p mimics reduced HIF-1α expression markedly and suppressed the activation of microglia and the release of inflammatory mediators, which relieved epileptic seizures of VPA-resistant epilepsy." (PMID 34497517, 2021). "In order to efficiently find the miRNA that regulates HIF-1α in VPA-resistant epilepsy, this study firstly performed integrated bioinformatics analysis on the hippocampal tissue of patients with drug-resistant epilepsy in public databases referring to the previous method." (PMID 34497517, 2021). "HIF-1α and Iba-1 co-localized in the hippocampus of mice with VPA-resistant epilepsy." (PMID 34497517, 2021). "In our current study, further inhibition of DAPK expression was found to regulate and decrease the expression of p-DAPK, HIF-1α, and VEGF in both human EPI-ECs/EPI-astro cells obtained from drug-resistant epilepsy, implying a link between DAPK activation, HIF-1α, and VEGF expression." (PMID 30414085, 2019). "We did not observe differential RNA or protein expression of HIF-1α and its target VEGFA between the epileptogenic GBMs and tumors that did not cause epilepsy." (PMID 30621209, 2019). "The study by Li Jie suggests that the activation of HIF-1α may be involved in the process of epileptogenesis but not in the acute stage of epilepsy." (PMID 39408863, 2024). "Thus, miR-485 alleviates neuronal damage and epilepsy by inhibiting HDAC5, HIF1α, and PFKFB3." (PMID 34021541, 2021).
esophageal squamous cell carcinoma (25 papers, 2013 to 2026). Esophageal squamous cell carcinoma (ESCC) is a type of esophageal carcinoma (EC) that can affect any part of the esophagus, but is usually located in the upper or middle third. "STAT3 inhibitors suppress STAT3 activation, down-regulate HIF-1α expression, and up-regulate the radiosensitivity of esophageal squamous cell carcinoma (ESCC) in vivo and in vitro." (PMID 38778409, 2024). "Under hypoxia, KDM3A was increased and co-localized with hypoxia-inducible factor HIF-1α in esophageal squamous cell carcinoma (ESCC)." (PMID 36797239, 2023). "An EIF5A2 increase has also been reported in esophageal squamous cell carcinoma and was shown to promote cell migratory and invasive abilities via the HIF1α-mediated signaling pathway." (PMID 27376958, 2016). "For esophageal squamous cell carcinoma, an evident higher 3-year OS rate (near to 63.0%) was observed in Beclin 1 positive subgroup, particularly in the patients with HIF-1α low expression context." (PMID 24303007, 2013). "Interestingly, eIF5A2 positively regulates the expression of HIF-1α in esophageal squamous cell carcinoma cell lines." (PMID 35931669, 2022). "Our previous study found that in esophageal squamous cell carcinoma cells, silencing Nrf2 expression could inhibit HIF-1α expression and reduce cell invasion under hypoxic conditions." (PMID 35417854, 2022). "CircPUM1 is positively correlated with HIF1α accumulation under CoCl2-induced intracellular hypoxic-like condition in esophageal squamous cell carcinoma (ESCC) cell lines." (PMID 38577612, 2024). "The expression level of circPUM1 is positively correlated with HIF1α accumulation under CoCl2-induced intracellular hypoxic-like condition in esophageal squamous cell carcinoma (ESCC) cell lines." (PMID 35153295, 2022). "HIF-1α was found to be overexpressed in esophageal squamous cell carcinoma (ESCC), and in vitro and in vivo experiments demonstrated that PX-478 has significant antitumor activity against HIF-1α-overexpressing ESCC tumors." (PMID 36139386, 2022). "This study explored the role of ovarian tumor deubiquitinase 7B (OTUD7B) in esophageal squamous cell carcinoma (ESCC) in the context of m6A methylation and the hypoxia-inducible factor-1α (HIF-1α) pathway." (PMID 40746896, 2025). "UBE2S, HIF‐1α, and FOXM1 in esophageal squamous cell carcinoma and their relationship with clinicopathological features." (PMID 41427004, 2025). "Interestingly, hypoxic stress induces the cytoplasm-to-nucleus translocation of eIF5A2 protein in esophageal squamous cell carcinoma (ESCC) cell lines, and eIF5A2 in the nucleus, promotes the transcription of HIF1α by binding to the promoter region of HIF1α." (PMID 32368188, 2020). "Studies reveal that HIF-1α upregulates insulin-like growth factor 1 (IGF1) secretion, which sustains the self-renewal capacity and stemness features of esophageal squamous cell carcinoma (ESCC) stem cells, ultimately promoting therapeutic resistance and tumor recurrence." (PMID 40755775, 2025).
laryngeal carcinoma (25 papers, 2012 to 2026). Carcinoma that arises from the laryngeal epithelium. "HIF‐1α and Glut‐1 are two important hypoxic markers associated with radioresistance in laryngeal carcinoma." (PMID 35415942, 2022). "At least one study has shown the limitations associated with inhibiting HIF-1α alone to improve radiosensitivity, thus, more effective strategies to enhance the radiosensitivity of laryngeal carcinoma need to be investigated." (PMID 28410229, 2017). "Our previous research showed a robust association between Glut‐1 and HIF‐1α in laryngeal carcinoma." (PMID 35415942, 2022). "Furthermore, HIF‐1α overexpression in laryngeal carcinoma caused radioresistance in AMC‐HN3 cells exposed to hypoxia." (PMID 35415942, 2022). "There are further reports that higher levels of HIF-1α can be associated with hypoxia-mediated multi-drug resistance in patients undergoing chemotherapy via the inhibition of drug-induced apoptosis of laryngeal cancer cell, leading to a decrease in drug accumulation within tumour cells." (PMID 30840126, 2019). "HIF-1α has been associated with a poor prognosis in laryngeal carcinoma." (PMID 28410229, 2017). "Several studies have focused on whether HIF-1α expression in human laryngeal carcinoma tissue is associated with tumor progression and lymph node metastasis." (PMID 23946810, 2013). "More than half of patients (56%) with advanced laryngeal carcinoma presented with mRNA HIF-1α upregulation (RQ > 2), and mRNA HIF-2α overexpression was evident in only 10% of the cases." (PMID 38607072, 2024). "For instance, STAT3/HIF-1α signaling pathway activation augments laryngeal cancer cell resistance to cisplatin." (PMID 37628777, 2023). "In a previous study, we confirmed that CRISPR/CAS9‐mediated Glut‐1 and HIF‐1α double knockout robustly reduced the proliferation, migration and invasion of laryngeal carcinoma HEp‐2 cells, possibly by modulating the PI3K/Akt signalling pathway." (PMID 35415942, 2022). "The role of Glut‐1 and HIF‐1α knockout on radiotherapy resistance was verified in another laryngeal carcinoma cell line Tu686." (PMID 35415942, 2022). "In this study, IGF‐1 treatment activated PI3K‐Akt‐mTOR signalling pathway, enlarged the resistance to radiotherapy, and elevated glucose uptake and the expression of HIF‐1α and Glut‐1 in laryngeal cancer cells." (PMID 35415942, 2022). "In conclusion, the findings in this study suggest that both the PI3K/Akt/mTOR signalling pathway and HIF‐1α/Glut‐1 are activated in hypoxic tumour cells, thereby facilitating glucose uptake radioresistance in laryngeal carcinoma cells." (PMID 35415942, 2022). "The protein levels of Glut‐1 and HIF‐1α in laryngeal carcinoma Tu212 cells were significantly elevated under hypoxic conditions compared with normoxic conditions." (PMID 35415942, 2022). "In the present study, we investigated the expression levels of Glut‐1 and HIF‐1α in X‐ray‐irradiated laryngeal carcinoma under hypoxic conditions." (PMID 35415942, 2022). "In the present study, we investigated the effects of radiation combined with an agonist or antagonist of the PI3K/Akt pathway, on the expression levels of Glut‐1 and HIF‐1α in laryngeal carcinoma Tu212 cells exposed to normoxic or anoxic conditions." (PMID 35415942, 2022). "HIF‐1α and/or Glut‐1 knockout facilitated radiosensitivity in laryngeal carcinoma Tu212 cells by regulation of the PI3K/Akt/mTOR pathway." (PMID 35415942, 2022). "Greater tumour necrosis areas were verified in Glut‐1 and/or HIF‐1α knockout tumours in the presence of irradiation, indicating that Glut‐1 and/or HIF‐1α knockout improved radiosensitivity in laryngeal carcinoma cells." (PMID 35415942, 2022). "Our previous study indicated that hypoxia‐inducible factor 1α (HIF‐1α) and glucose transporter 1 (Glut‐1) double knockout reduced tumour biological behaviour in laryngeal carcinoma cells." (PMID 35415942, 2022).